HK2 (hexokinase 2)
Diseases named in the same sentence as HK2 in open-access papers (continued):
Sharing a sentence is not in itself a finding about the gene and the disease.
lymphoma (continued). "The expressions of HK2 and PDK1 in the presence of exosomes from CAF1 and CAF2 were higher than those from CAF3 and CAF4, indicating that glycolysis in lymphoma cells was increased in the presence of exosomes from CAF1 and CAF2." (PMID 33994542, 2021). "In lymphoma cells co-cultured with CAF1 and CAF2, the expressions of HK2 and PDK1, key enzymes of glycolysis, were higher than in those with CAF3 and CAF4." (PMID 33994542, 2021). "RT-PCR expression profiling of various DLBCL cell lines demonstrated that expression of key enzymes GLUT1, HK2, FAS and Cyt-C was induced during hypoxia in lymphoma cell lines and patient derived malignant B cells." (PMID 29335581, 2018). "We therefore performed screening of lymphoma tissue microarrays (Biomax) to validate the expression of metabolic markers GLUT1, Cyt-C and HK2 in human DLBCL patient samples and explore their prognostic importance." (PMID 29335581, 2018). "We also performed knockdown of HK2 in another aggressive lymphoma cell line, SUDHL2, to rule out the possibility of a cell line-specific effect." (PMID 29335581, 2018). "To identify functional relevance of changes in GLUT1, HK2 and Cyt-C in DLBCL, we performed screening of tissues derived from lymphoma patients and normal individuals, which predicted HK2 as a critical regulator of lymphoma development." (PMID 29335581, 2018). "However, FAP was expressed in some lymphomas without HK2 and/or GLUT1." (PMID 39595051, 2024). "Even though there has been a lot of interest into targeting HK2, particularly as its expression has been shown to positively correlate with FDG-uptake in lymphoma, no inhibitor has yet entered clinical trials." (PMID 36428647, 2022).
ischemia (23 papers, 2012 to 2025). A hypoperfusion of the BLOOD through an organ or tissue caused by a PATHOLOGIC CONSTRICTION or obstruction of its BLOOD VESSELS, or an absence of BLOOD CIRCULATION. "By contrast, IPC does not reduce the accumulation of succinate, a proposed source of ROS, during ischemia or the rate of its subsequent decline on reperfusion but does prevent HK2 loss from mitochondria during ischemia." (PMID 32579577, 2020). "This provides an explanation of the very close correlation between the extent of HK2 loss from mitochondria during ischemia and the extent of injury (infarct size) on subsequent reperfusion." (PMID 28689004, 2017). "Dissociation of bound HK2 is associated with an increase loss of cytochrome c from the mitochondria during ischemia and an enhanced sensitivity to mPTP opening." (PMID 28689004, 2017). "Cardioprotective protocols such as IP prevent HK2 loss from mitochondria during ischemia and so prevent both phases of mPTP opening." (PMID 28689004, 2017). "IP, by preventing the HK2 loss and contact site destabilization during ischemia, will prevent these secondary increases in [Ca2+] and ROS and thus attenuate the resulting cell death and infarct development." (PMID 27907091, 2016). "In this regard, ischemia is associated with a decrease in the amount of hexokinase 2 (HK2) bound to mitochondria which is caused by accumulation of glucose-6-phosphate (G6P) and a drop in cytosolic pH that occurs as a result of enhanced glycolysis during this phase." (PMID 32579577, 2020). "Indeed, there is a strong correlation between the extent of HK2 loss from mitochondria during ischemia and infarct size on subsequent reperfusion." (PMID 28689004, 2017). "HK2 binding stabilises contact sites and thus it would be predicted that the loss of HK2 during ischemia might lead to contact site breakage." (PMID 28689004, 2017). "The data we present in this article support the hypothesis that a critical factor in the determining the extent of damage (infarct size) during reperfusion after ischemia is loss of HK2 bound to mitochondria." (PMID 23525412, 2012). "Recent studies have found that glucose 6-phosphate accumulation and decreased pH after prolonged ischemia could affect mitochondrial HK2 dissociation, and that enhancing the binding of HK2 to the outer mitochondrial membrane alleviates myocardial injury caused by ischemia and hypoxia." (PMID 34741026, 2021). "Thus, dissociation of mt-HK2, which is known to associate with contact sites, could co-operate with Drp1 and Dyn2 recruitment to cause their destabilization in ischemia." (PMID 32579577, 2020). "The administration of Ginkgo biloba extract (EGb) significantly reduced infarct volume and inflammatory cytokine levels in ischemia/reperfusion mice via inhibiting the hypoxia-inducible factor-1α (HIF-1α)/HK2 signaling pathway." (PMID 40354372, 2025). "In contrast, transient glycogen depletion prior to acute ischemia is cardioprotective as it reduces the dissociation of hexokinase 2 from mitochondria and therefore inhibits the opening of mitochondrial permeability transition pore." (PMID 40940740, 2025). "By contrast, a strong correlation has been observed between the extents of hexokinase 2 (HK2) dissociation from mitochondria at the end of ischemia with the extent of mPTP opening on reperfusion." (PMID 37460667, 2023). "More in general, mitochondrial HK2 shields from cardiac ischemia/reperfusion injury, at least partially by slowing adenine nucleotide exchange via inhibition of Voltage Dependent Anion Channel (VDAC) on the OMM." (PMID 33946854, 2021). "Taken together, these data imply that the increased sensitivity to mPTP opening observed after ischemia, like the changes in outer membrane permeability and respiration, must occur downstream of HK2 dissociation from mitochondria." (PMID 32579577, 2020).
ischemia (continued). "First, the amplitude of the Ca2+-induced decrease in LS of HK2-depleted pre-ischemia mitochondria was lower than for un-depleted controls, but still higher than end-ischemia mitochondria." (PMID 32579577, 2020). "Overall our data suggests that HK2 dissociation alone is insufficient to account for the reported deleterious effects of ischemia on mitochondrial respiration and OMMP." (PMID 32579577, 2020). "This agrees with our previous findings where variations to the standard perfusion protocol led to different amounts of mt-HK2 being retained at end of ischemia, correlating with cardiac damage at reperfusion." (PMID 32579577, 2020). "We further investigated how KD affects glycolysis, and found that expression of the HK2 protein, a glycolytic enzyme, was also decreased in the hind limb tissue of KD mice both before and after ischemia, but with a more significant decrease in ischemic tissue than that in mice in the ND group." (PMID 36038886, 2022). "Indeed, we found a strong inverse correlation between the amount of mt-HK2 remaining at end of ischemia and the infarct size upon subsequent reperfusion." (PMID 32579577, 2020). "In vitro HK2 dissociation alone cannot replicate ischemia-induced effects on mitochondrial function implying that in vivo dissociation of HK2 modulates end-ischemia mitochondrial function indirectly perhaps involving interaction with mitochondrial fission proteins." (PMID 32579577, 2020). "Zuurbier and colleagues demonstrated a progressive loss of bound mitochondria-bound HK2 during ischemia of the heart and we confirmed this, showing substantial loss of mitochondrial HK2, but not HK1, after 30 min global ischemia." (PMID 28689004, 2017). "Possible mechanisms by which IP may attenuate HK2 dissociation from mitochondria during ischemia have been comprehensively reviewed elsewhere and are only briefly summarised here." (PMID 28689004, 2017). "Rather, we suggest that it is elevated [Ca2+] that initiates mPTP opens on reperfusion and that IP attenuates other factors that sensitise the mPTP to [Ca2+], including the well-established dissociation of hexokinase 2 (HK2) from its mitochondrial binding site that occurs during ischemia." (PMID 28689004, 2017). "Indeed, there is a very strong inverse correlation between the amount of HK2 remaining bound to mitochondria at the end of ischemia and the infarct size after 120 min of reperfusion." (PMID 27907091, 2016). "In the present investigation we have applied a battery of biochemical techniques and ultrastructure imaging tools to assess whether mt-HK2 dissociation alone is sufficient to reproduce some or all of the changes in mitochondrial function observed following ischemia." (PMID 32579577, 2020). "In further accord with an important survival role of mitochondrial HK2, the AKT/HK2 axis shields neurons from ischemia." (PMID 33946854, 2021). "The binding of HK-2 plays an anti-apoptotic role and inhibits MPTP opening and there is an inverse correlation between the extent of HK-2 binding at the end of ischaemia and infarct size." (PMID 24885907, 2014). "Intriguingly, a previous study showed that HK2 separation from mitochondria triggered Parkin‐mediated mitophagy that was independent of PINK1 pathway in response to ischemia." (PMID 36514923, 2023). "The fact that removal of mt-HK2 from IPC mitochondria does not increase mPTP activity to the level observed in end-ischemia mitochondria provides evidence that the IPC-mediated inhibition of mPTP opening is not caused directly by the bound HK2." (PMID 32579577, 2020). "We have shown that release of mitochondrial-bound HK2 in vivo during ischemia does not affect end-ischemia mitochondrial function directly." (PMID 32579577, 2020). "Second, the rate of ADP-induced LS change of HK2-depleted IPC end-ischemia mitochondria was slower than for the same mitochondria without HK2-depletion, but still higher than end-ischemia mitochondria." (PMID 32579577, 2020).
ischemia (continued). "A promising additional candidate for regulating the initial phase of mPTP opening is mitochondrial bound HK2 which dissociates from the mitochondria during ischemia, but not following IP." (PMID 28689004, 2017). "One such is mitochondria-bound hexokinase 2 (HK2) which dissociates from mitochondria during ischemia in control hearts but not those subject to IP." (PMID 28689004, 2017). "We provide data to suggest that this may be explained by the ability of bound HK2 to prevent the breakage of mitochondrial contact sites between the inner mitochondrial membrane (IMM) and the OMM during ischemia." (PMID 23525412, 2012). "Thus, we propose that the ability of IPC to maintain mitochondrial morphology and OMM integrity during ischemia, and so facilitate cytochrome c retention, is not a direct effect of preventing mt-HK2 dissociation." (PMID 32579577, 2020). "However, our data reveal that HK2 dissociation in vitro does not replicate ischemia-induced effects on these parameters which leads us to conclude that release of mitochondrial-bound HK2 in vivo must affect mitochondrial morphology and function indirectly." (PMID 32579577, 2020). "This implies that the entities responsible for OMMP are not pre-inserted in the mitochondria during ischemia such that they could initiate their action upon HK2 release." (PMID 32579577, 2020). "Although these studies have identified ischemia-induced events upstream and downstream of HK2 displacement, it has not been established whether mt-HK2 dissociation is the primary signal mediating the ischemia-induced changes to mitochondria that enhance mPTP opening on reperfusion." (PMID 32579577, 2020).
non-small cell lung carcinoma (22 papers, 2013 to 2025). A group of at least three distinct histological types of lung cancer, including non-small cell squamous cell carcinoma, adenocarcinoma, and large cell carcinoma. "Another preclinical study on non-small cell lung carcinoma (NSCLC) cells revealed that PL treatment decreased the levels of HK2, an enzyme of the glycolysis process which was found to be involved in tumor progression." (PMID 36046754, 2021). "Furthermore, HK2 overexpression in tumor cells has been shown to promote the proliferation of non-small cell lung cancer cells and tumor growth, highlighting its role in cancer development." (PMID 40395233, 2025). "Additionally, 2DG enhances the sensitivity of non-small cell lung cancer to crizotinib by inhibiting both HK2-mediated glycolysis and the AKT/mTOR signaling pathway." (PMID 39609317, 2024). "The SIRT6 may promote the growth of erlotinib-resistant non-small cell lung cancer cells by activating the HIF-1α/HK2 signaling axis to promote aerobic glycolysis in tumor cells." (PMID 39876842, 2024). "LncRNA DUXAP8 could directly sponge miR-409-3p to regulate HK2 expression, and promote non-small-cell lung cancer cell growth, and metastasis." (PMID 36072431, 2022). "Moreover, attenuation of HK2-mediated glycolysis by small compounds impaired the malignant phenotypes of various human cancers, such as non-small cell lung cancer and colon cancer." (PMID 32424132, 2020). "For instance, USP7 (ubiquitin-specific protease 7) promotes non-small-cell lung cancer (NSCLC) cell metabolism by activating c-Abl and HK2." (PMID 41330897, 2025). "Compound 24 inhibited the non-small-cell lung cancer (NSCLC) both in vitro and in vivo by downregulating glycolysis, decreasing HK2 expression and inducing mitochondrial apoptosis." (PMID 40941984, 2025). "lncRNA CYB561-5 interacts with protein basigin (Bsg) to upregulate HK2 and PFK1 expression in non-small cell lung cancer (NSCLC)." (PMID 41361062, 2025). "The glycolytic enzymes hexokinase 2 (HK2) and the M2 isoform of pyruvate kinase (PKM2) were also shown to be substrates of CMA degradation, in ovarian and non-small cell lung cancers, respectively." (PMID 33312955, 2020). "Importantly, we showed the short hairpin RNA (shRNA)-mediated attenuation of Set7/9 augmented c-Myc, GLUT1, HK2, ALDOA, and LDHA expression in non-small cell lung cancer (NSCLC) cell lines, not only at the transcriptional but also at the protein level." (PMID 34692483, 2021). "In addition, PD-L1 was key in mediating IFNγ regulation of glucose and glutamine metabolism, although not through transcriptional regulation of metabolic enzymes and unlike a report of PD-L1 regulating HK2 in non-small cell lung cancer." (PMID 35656514, 2022).
Arthritis (21 papers, 2017 to 2025). Inflammation of a joint. "Gene associations with HK2 expression were identified by examining single-cell RNA sequencing (scRNA-seq) data from murine models of arthritis." (PMID 37529037, 2023). "Results show that both 2-DG and MitoQ reduce paw swelling and arthritis score, and the expression of HK2 and LDH in ankle joints." (PMID 40599793, 2025). "In a study, the authors injected HK2 inhibitor, 3-bromopyruvate (BrPA), into mice with arthritis models, which inhibited glycolysis levels and resulted in a significant decrease in arthritis levels." (PMID 38482018, 2024). "In vivo data also show that dissociation of HK2 from mitochondria in arthritic mouse models attenuates arthritis severity." (PMID 37529037, 2023). "The presence of HK2 and GLS across various cell types and associated gene expression in human synovial cells and a murine model of arthritis was evaluated by scRNA-seq." (PMID 37730663, 2023). "Ablation of HK2 significantly reduced severity of arthritis and bone and cartilage damage in KBxN serum transfer induced arthritis." (PMID 35252279, 2022). "HK2 is expressed explicitly in the synovial lining of RA and has a regulatory effect on the severity of arthritis, bone and cartilage damage in mice, and the invasion function of FLS31." (PMID 34521930, 2021). "More specifically, ablation of glycolytic genes or treatment with 3-bromopyruvate, which antagonizes HK2, significantly reduced the severity of several murine arthritis models." (PMID 31428089, 2019). "Other glycolytic inhibitors, such as 3-bromopyruvate (BrPA), a specific HK2 inhibitor decreased arthritis score and histological scores in the SKG mouse model." (PMID 31057554, 2019). "An abrogation of the aggressive phenotype of RASF by 2-DG, a non-metabolizable glucose analogue which blocks glycolysis downstream of HK2, has also been described by others, and 2-DG has been shown to be effective in reducing the severity of arthritis in a mouse model." (PMID 33588937, 2021). "Here we demonstrated that 3-bromopyruvate (BrPA), a specific HK2 inhibitor, significantly decreased the arthritis scores and the histological scores in SKG mice, with a significant increase in Treg cells, decrease in Th17 cells, and decrease in activated DCs in the spleen." (PMID 28186160, 2017). "Given HK2 selective overexpression in inflamed RA synovium, its small role in T cells, and its expression in a very limited number of adult tissues, HK2 is an attractive selective target for arthritis therapy that is safer than global glucose metabolism inhibition." (PMID 31428089, 2019). "HK2 inhibitors, such as 2-DG, have been widely studied and shown to counteract inflammation, proliferation, and invasion in RA-FLS, thereby reducing the severity of arthritis." (PMID 40165083, 2025).